PGR (progesterone receptor)
Diseases named in the same sentence as PGR in open-access papers (continued):
Sharing a sentence is not in itself a finding about the gene and the disease.
breast cancer (continued). "In the Breast International Group's Femara-Tamoxifen trial, also known as BIG 1–98, 5 years of adjuvant letrozole was compared with 5 years of tamoxifen in postmenopausal women with ER-positive and/or PgR-positive breast cancer." (PMID 17892469, 2007). "A high prevalence of PGR, HSD17B4, and CDH13 methylation has been associated with HER-2/neu-positive breast cancer." (PMID 17764565, 2007). "In human T47D breast carcinoma cells, δEF1 is up-regulated by progesterone via both isoforms of the progesterone receptor (PR)." (PMID 17997862, 2007). "E2 induces lactate dehydrogenase activity in MCF-7 human breast cancer cells, and is elevated in estrogen receptor positive or progesterone receptor positive tumors." (PMID 17010207, 2006). "The amounts of estrogen receptor (ER) and progesterone receptor (PgR) in a primary tumor are predictive of the response to endocrine therapies of breast cancer." (PMID 16417653, 2006). "Tamoxifen, a selective estrogen receptor modulator (SERM), is the standard drug for endocrine therapy in patients with estradiol and/or progesterone receptor positive breast cancer." (PMID 16972993, 2006). "The correlations of Fra-1 with estrogen receptor (ER), progesterone receptor (PR) and ErbB2 receptor status were analyzed in breast cancer patients in order to further explore the role of Fra-1 in the diagnosis of breast cancer." (PMID 17192200, 2006). "Our results are similar to those of Uehara, who also evaluated estrogen and progesterone receptor positivity in breast cancer of women treated with tamoxifen." (PMID 16972993, 2006). "Biological features of endocrine responsiveness, namely the overexpression of estrogen receptor (ER) and/or progesterone receptor (PgR), are important predictive and prognostic markers in breast cancers." (PMID 16417653, 2006). "The objective of the present study was to examine the relationship between reproductive events and tumor stage, grade, estrogen receptor and progesterone receptor status, and survival in women diagnosed with early-onset breast cancer." (PMID 15987461, 2005). "As first-line treatment of advanced breast cancer in postmenopausal women with ER-positive and/or PgR-positive tumours, fulvestrant appears to have a similar efficacy to tamoxifen." (PMID 15094759, 2004). "In summary, as second-line therapy for postmenopausal women with ER-positive and/or PgR-positive advanced breast cancer who have progressed on prior endocrine treatment, fulvestrant is clearly an effective therapy that offers equal efficacy to anastrozole." (PMID 15094759, 2004). "Fulvestrant has been shown to significantly reduce cellular levels of the ER and progesterone receptor in both preclinical studies and in clinical trials of postmenopausal women with primary breast cancer." (PMID 15094758, 2004). "We used data from 765 cases and 564 controls in the population-based Australian Breast Cancer Family Study to investigate whether, in women under the age of 40, the profile of risk factors differed between breast cancer subtypes defined by joint oestrogen and progesterone receptor status." (PMID 14583766, 2003). "Our results agree with other studies on oestrogen receptor, progesterone receptor, and Her2/neu on breast cancer, which report that most paraffin-embedded materials up to an age of at least 68 years are still useful for immunohistochemical analysis." (PMID 12778072, 2003). "The traditional prognostic factors of breast carcinoma include the size of the primary tumour, axillary lymph node involvement, tumour grade, oestrogen or progesterone receptor status of the primary tumour and menopausal status of the patients." (PMID 14520459, 2003). "The progesterone receptor (PR) is an important prognostic marker in breast cancer as well as a marker of responsiveness to endocrine therapies." (PMID 10408841, 1999).
breast cancer (continued). "The prognostic value of oestrogen receptor (ER) and progesterone receptor (PR) was estimated through a multicentric study of 2257 operable breast cancer patients followed up for a median of 8.5 years." (PMID 8664127, 1996). "Competitive polymerase chain reaction assays have been developed for the quantitation of oestrogen receptor mRNA and two oestrogen-regulated mRNAs (progesterone receptor and pNR-2/pS2) in breast cancer cells." (PMID 8519655, 1995). "When 144 breast cancers were categorised in terms of combinations of oestrogen receptor (ER) and progesterone receptor (PgR) status, breast cancers which were positive for both receptors were found to contain the highest t-PA activity and antigen." (PMID 8394731, 1993). "The correlation between prolactin (PRLR) and oestrogen (ER) or progesterone receptors (PgR) in breast cancer and a possible prognostic significance of PRLR at 10 year follow-up have been investigated in the Naples (GUN) adjuvant trial." (PMID 2223582, 1990). "Assessment of progesterone receptor expression by breast cancers containing oestrogen receptors indicated that aneuploid tumours were as likely to express PR as were diploid tumours." (PMID 3004547, 1986). "Oestrogen and progesterone receptor assays were performed in 286 women with primary breast cancer, and the patient group was followed up for a minimum of 24 months." (PMID 6498064, 1984). "One hundred and nineteen patients with breast cancer had 2 or more lesions removed for oestrogen (REc) or progesterone receptor (RPc) assay, either synchronously (on 38 occasions) or after an interval (on 91 occasions)." (PMID 6682673, 1983). "This study demonstrates that bisphenol analogues, particularly BPAF, bind to progesterone receptor, promoting breast cancer cell proliferation, migration, and mammary tumor growth, indicating that bisphenol A substitutes may pose equal or greater health risks." (PMID 41201099, 2026). "Breast cancer (BC) is the most common malignant neoplasm in the United Kingdom and requires additional testing for estrogen receptor (ER), progesterone receptor (PR), and human epidermal growth factor receptor-2 (HER2) status at the time of histological diagnosis." (PMID 42302265, 2026). "In addition to their morphological classification, breast cancers are categorized based on ER, progesterone receptor (PR), and HER2 expression." (PMID 39858015, 2025). "In the metastatic niche the breast cancer cells may express a different pattern of the receptors, ER, PgR, and HER-2." (PMID 41373503, 2025). "Therefore, the mechanism of action of rolipram in both endoplasmic reticulum/progesterone receptor–positive breast cancer and TNBCs, and the crosstalk between PKA and Hh, was explored in this study." (PMID 39880092, 2025). "Regarding the subtypes of breast cancer, for the cases with ER + and/or PgR +, HER2 −, the number began to decrease in May 2020, showing an 8% reduction compared with that of the previous year." (PMID 40353952, 2025). "The clinical categorization of breast cancer is based on the expression status of specific receptors, including the estrogen receptor (ER), progesterone receptor (PgR), human epidermal growth factor receptor 2 (HER2), and the Ki-67 proliferation marker protein." (PMID 40136347, 2025). "To further investigate the expression pattern of ESPL1 across various breast cancer (BC) subtypes, we utilized the bc-GenExMiner v5.0 database, stratifying the data based on estrogen receptor (ER), progesterone receptor (PR), and triple-negative breast cancer (TNBC) status." (PMID 41268575, 2025). "At the same time, one report speculated that gas plasma susceptibility relates to the expression of ER/PR (estrogen receptor/progesterone receptor) on HER2-positive breast cancer cells." (PMID 41008962, 2025).
breast cancer (continued). "Breast cancer represents a highly heterogeneous malignancy, in which three principal biomarkers, the estrogen receptor (ER), progesterone receptor (PR), and human epidermal growth factor receptor 2 (HER2), play a central role in molecular classification and therapeutic strategies guidance." (PMID 41373619, 2025). "Additionally, jadomycins are equally potent against estrogen receptor–positive, progesterone receptor–positive, and human epidermal growth factor–overexpressing breast cancer cells." (PMID 40253988, 2025). "Currently the arrangement of systemic adjuvant therapy for breast cancer is based on clinical and pathological prognostic and/or predictive factors such as estrogen receptor (ER), progesterone receptor (PgR) and human epidermal growth factor receptor type II (HER2) status." (PMID 40927672, 2025). "This study offers a template for biologically informed early-phase therapeutic cancer prevention trials and demonstrates the potential for premenopausal breast cancer prevention with progesterone receptor antagonists through stromal remodelling and luminal progenitor suppression." (PMID 41193807, 2025). "Breast cancer can be categorized into three primary subtypes based on the expression levels of estrogen receptor (ER), progesterone receptor (PR), and human epidermal growth factor receptor 2 (HER2): hormone receptor-positive, HER2-positive, and triple-negative breast cancer (TNBC)." (PMID 40134434, 2025). "In cases of clinically and radiologically axilla-negative, early-stage breast cancer, a progesterone receptor level below 80% in Tru-cut biopsy increases the risk of axillary lymph node metastasis." (PMID 40283001, 2025). "The molecular subtypes of breast cancer, based on immunohistochemical expression, are typically classified into four categories: oestrogen receptor-positive (ER+), progesterone receptor positive (PR+), human epidermal growth factor receptor-positive (HER2+), and triple-negative (TNBC)." (PMID 39905197, 2025). "In breast cancer patients, there is no consensus on a threshold value for progesterone receptor to predict the risk of axillary lymph node metastasis." (PMID 40283001, 2025). "Breast cancer is a highly heterogeneous disease, and it can be classified into molecular subtypes based on the expression of key receptors: estrogen receptor (ER), progesterone receptor (PR), and human epidermal growth factor receptor 2 (HER2)." (PMID 41007650, 2025). "To assess the cellular architecture and expression of typical breast cancer markers (estrogen and progesterone receptor, HER2, and the proliferation marker Ki67), we performed histologic staining on entire organoids still embedded in their growth matrix of BME." (PMID 40022208, 2025). "One such development involves multilayered, surface amino-modified single-band up-conversion nanoparticles (sb-UCNPs) conjugated with antibodies specific to breast cancer biomarkers like progesterone receptor (PR), estrogen receptor (ER), and human epidermal growth factor receptor 2 (HER2)." (PMID 40573996, 2025). "PGR, as a progesterone receptor agonist, also plays a significant role in breast cancer treatment." (PMID 40170854, 2025). "In comparison, luminal subtype breast cancers (expressing estrogen receptor and/or progesterone receptor) show a median infiltration of sTILs of between 7 and 10% and of iTILs of between 1.5 and 5%, with a heterogenous prevalence of LPBC ranging from 2.9 to 12%." (PMID 40362529, 2025). "Most triple negative (human epidermal growth factor receptor 2 (HER-2), progesterone receptor (PR), and estrogen receptor (ER) negative) breast cancers, as well as high-risk luminal HER-2 negative tumors, are treated with chemotherapy." (PMID 40459761, 2025).
breast cancer (continued). "Subtyping of breast cancer, based on oestrogen receptor (ER), progesterone receptor (PR) and human epidermal growth factor receptor 2 (HER2) expression levels, classifies it into Luminal‐A, Luminal‐B, HER2‐positive and triple‐negative breast cancer (TNBC) subtypes." (PMID 40070134, 2025). "Paget cells share immunohistochemical features with the associated breast cancer cells, often lacking estrogen and progesterone receptor expression." (PMID 40486154, 2025). "Docking scores are reported against three breast cancer targets: progesterone receptor (PR, PDB 2W8Y), HER2 tyrosine kinase domain (PDB 7JXH), and estrogen-receptor-α ligand-binding domain (PDB 6VJD), together with pIC50 values predicted by the QSAR model (pIC50 = −log10 IC50, M)." (PMID 40806603, 2025). "When analyzing the original breast cancer, the median value of estrogen receptor expression was 90% (95% CI 87.4–90.0, ranging from 8 to 100), progesterone receptor 37.5% (95% CI 22.0–55.0, ranging from 0 to 100), and Ki67 23.0% (95% CI 21.4–25.0, ranging from 1 to 85)." (PMID 39338149, 2024). "Current clinical practice categorizes breast cancer into three subtypes based on immunohistochemistry (IHC) tests for estrogen receptor (ER), progesterone receptor (PR), and erythroblastic oncogene B/human epidermal growth factor receptor 2 (ErbB2/HER2) expression." (PMID 38892243, 2024). "The most aggressive form of breast cancer types are known as triple-negative, which lack expression of hormone receptors, including estrogen receptor (ER) and/or progesterone receptor (PR) as well as the expression of the human epidermal growth factor receptor 2 (HER2)." (PMID 38675909, 2024). "Breast cancer is a highly heterogeneous disease, which can be classified into four molecular subtypes according to the expression levels of estrogen receptor (ER), progesterone receptor (PR), and human epidermal growth factor receptor 2 (HER2)." (PMID 38254782, 2024). "Mammary cancers are also classified into four subtypes according to the expression of immunohistochemical markers including estrogen receptor (ER), progesterone receptor (PR), and receptor of human epidermal growth factor 2 (HER-2 or EGFR-2): I. Luminal A (ER+ and/or PR+, and HER-2−), II." (PMID 38474142, 2024). "In 2002, a 46-year-old woman with a history of Raynaud’s syndrome and hypothyroidism was diagnosed with HR-positive [estrogen receptor (ER) 95%, progesterone receptor (PR) 95%] HER2-negative low-grade invasive cancer (NOS) of the right breast cancer (pT1cpN1aM0)." (PMID 39749028, 2024). "We also found RB1 mutations to be significantly depleted in B7-H3–high breast cancers that are hormone receptor (estrogen receptor/progesterone receptor) positive (HR+)/HER2 negative (1.6% vs. 8.7%, q < 0.0001)." (PMID 38709075, 2024). "In cells grown in 3D, progestins regulate a group of breast cancer-associated genes that are also regulated in 2D including CDH10, PGR, CHEK2, LSP1, TERT, SDPR, but also a new set of 3D-exclusive genes, associated to the ECM including members of the integrin family, Laminins, and AKT3." (PMID 38565950, 2024). "We analysed a large and well-characterized cohort of breast cancer cases with complete data on classical prognostic factors and relevant molecular markers, such as oestrogen receptor (ER), progesterone receptor (PgR) and HER2 as well as Cathepsin D’s role in response to tamoxifen therapy." (PMID 38578521, 2024). "Breast cancer is commonly classified into molecular subtypes based on the expression status of molecular markers, including ER, progesterone receptor (PR), hormone receptors (HRs), and HER2 (Luminal A, HR+ HER2-; Luminal B, HR+ HER2+; HER2: HR- HER2+; TNBC: HR- HER2-)." (PMID 39791720, 2024). "Breast cancer is classified into four subtypes, namely Luminal A, Luminal B, Her2-enriched, and triple-negative, which are determined by the expression levels of estrogen receptor (ER), progesterone receptor (PR), and ERBB2 receptor (HER2)." (PMID 39334351, 2024).
breast cancer (continued). "Breast cancer can be categorized into molecular subtypes based on estrogen receptor (ER), progesterone receptor (PR), and human epidermal growth factor receptor 2 (HER2) expression, namely, Luminal A, Luminal B, HER2-enriched, and triple-negative breast cancer (TNBC)." (PMID 39768178, 2024). "Selecting breast cancer treatment depends on the expression of the estrogen receptor (ER), progesterone receptor (PgR), and human epidermal growth factor receptor type 2 (HER2); however, there are instances of subtype discordance between primary and metastatic lesions." (PMID 39429386, 2024). "The essential role of ER and PgR in the growth of breast cancer is well acknowledged." (PMID 39497884, 2024). "One meta-analysis has shown breastfeeding associated with 10% risk reduction in estrogen receptor (ER) negative and progesterone receptor (PR) negative breast cancer, and a 20% risk reduction in TNBC." (PMID 38835377, 2024). "Based on the expression of estrogen receptor (ER), progesterone receptor (PR), and human epidermal growth factor receptor (Her2), breast cancer can be categorized into four molecular subgroups: luminal A type, luminal B type, Her2-positive type, and basal-like type." (PMID 38977630, 2024). "In addition, ADAMTS18 in invasive ductal carcinoma (IDC) of the breast is correlated not only with tumor histological grade but also with estrogen receptor (ER), progesterone receptor (PR), and Ki67, which are markers of breast cancer." (PMID 38482210, 2024). "The patient was diagnosed with breast cancer ER-positive, PgR-positive, and HER2-positive." (PMID 39429386, 2024). "High PTK7 mRNA protein expression was significantly associated with breast cancer-specific survival of ER-positive (p = 0.020), PgR-negative (p = 0.002), and HER2-negative patients (p < 0.001)." (PMID 39335176, 2024). "However, until recently, the NCDB did not report quantitative histologic parameters for variables such as estrogen receptor (ER), progesterone receptor (PR), and Ki-67 expression in breast cancer patients, limiting the accuracy of such models." (PMID 38879577, 2024). "Breast cancer could be classified based on the expression of these tumoral biomarkers: estrogen receptor (ER), progesterone receptor (PR), and human epidermal growth factor receptor 2 (HER2)." (PMID 39320560, 2024). "MCF‐7 is a frequently used breast cancer cell line obtained from a patient with luminal A breast cancer, which is distinguished by the presence of estrogen receptor (ER) and/or progesterone receptor (PR) expression and low levels of human epidermal growth factor receptor 2 (HER2)." (PMID 38349028, 2024). "Breast cancer is a heterogeneous disease, and accurate determination of basic biomarkers including estrogen receptor (ER), progesterone receptor (PR), and human epidermal growth factor receptor 2 (HER2) is crucial for selecting appropriate treatment for breast cancer patients." (PMID 38643429, 2024). "Therefore, to link the expression pattern of the canonical luminal breast cancer markers with the ‘proliferative’ ST_2‐associated SC clusters, we further investigated our scRNA‐seq datasets using the classification based on ESR1/PGR/MKI67 expressions." (PMID 38282415, 2024). "Triple negative breast cancer (TNBC) is generally defined as a type of breast cancer in which estrogen receptor (ER), progesterone receptor (PR) and human epidermal growth factor receptor 2 (HER2) are all expressed negatively, accounting for about 12%–17% of all breast cancers." (PMID 39372954, 2024). "Triple-negative breast cancer (TNBC) occurs when a patient is negative for estrogen receptor (ER), progesterone receptor (PR), and Her-2, and this variant represents approximately 15–20% of all breast cancers." (PMID 37372337, 2023).